RNF227 (ring finger protein 227)
Synonyms: LINC02581
Tractability: PROTAC: ubiquitination databases record sites on it.
Gene: Protein-coding gene on chromosome 17 (7,913,339 to 7,916,289, reverse strand). Ensembl gene ENSG00000179859.
Gene Ontology:
Molecular function: ubiquitin protein ligase activity
Biological process: protein ubiquitination
Homologues: Orthologues: chimpanzee RNF227 (98% identical), macaque RNF227 (91% identical), rabbit RNF227 (86% identical), guinea pig RNF227 (81% identical), pig RNF227 (80% identical), rat Rnf227 (79% identical), mouse Rnf227 (78% identical), dog RNF227 (77% identical), Drosophila melanogaster roq (18% identical). Paralogues in human: RNF224 (24% identical), RC3H1 (19% identical), RC3H2 (18% identical), RNF182 (18% identical), RNF228 (17% identical).